CD47 (CD47 molecule)
Diseases named in the same sentence as CD47 in open-access papers (continued):
Sharing a sentence is not in itself a finding about the gene and the disease.
tumor (continued). "In other words, for medium-sized tumors (100 to 400 mm3), given the same irradiation dose, CD47-KO is more effective in reducing the tumor than SIRPα-KO and anti-SIRPα, which in turn is more effective than anti-CD47." (PMID 41296731, 2025). "In HCT116-bearing mice, butyrate administration led to significantly higher CD47 expression in the tumor tissues." (PMID 39994810, 2025). "Blocking this interaction with monoclonal antibodies restores the capacity of innate immune cells to eliminate tumor cells, making CD47 an attractive target, particularly in hematologic malignancies." (PMID 41303525, 2025). "This is achieved by inhibiting the CD47 signal, commonly referred to as the “don’t eat me” signal, which is often used by tumor cells to evade the immune system." (PMID 40862764, 2025). "Although venetoclax is shown to be effective in inducing apoptosis and preventing tumor proliferation, it can induce the CD47 expression on cancer cells." (PMID 40469777, 2025). "Targeting CD47 or its receptor SIRPα has emerged as a promising therapeutic strategy to enhance anti-tumor immunity." (PMID 40655153, 2025). "This study employs neutrophils for the precise delivery of anti‐CD47 antibodies, combined with bacterial outer membrane vesicles, to enhance macrophage phagocytic function in the tumor microenvironment." (PMID 40287972, 2025). "CD47 protein expression, calculated as the percentage of tumor cells expressing CD47, has modest difference across the molecular subgroups; the CMS1 CRC subtype demonstrated a statistically significant but subtle increase in CD47 expression compared to CMS3." (PMID 41415295, 2025). "A subsequent study was conducted in order to confirm the results of the initial investigation,which had revealed the presence of high levels of CD47 expression in normal mouse tissues, as well as in mouse tumor tissues." (PMID 40070841, 2025). "Overall, KPC-tumor-bearing mice that received NDV-vectored CD47 blockade experienced a higher incidence of CR and were more resistant to re-challenge." (PMID 41322194, 2025). "Tumor cells often evade immune surveillance by overexpressing immune checkpoint proteins, such as PD‐L1 and CD47, which inhibit immune cell activity." (PMID 40035259, 2025). "Individual CD47 nanobody or IR700@Nb289‐OMVs plus NIR irradiation resulted in a slight delay in tumour progression in the abdominal metastatic model compared with the control treatment." (PMID 40240911, 2025). "Within the tumor microenvironment, the combined upregulation of CD47 and CD24 likely amplifies “don’t eat me” signaling, thereby enhancing resistance to macrophage-mediated phagocytosis and facilitating immune evasion." (PMID 41303350, 2025). "CD47 protein expression was higher on tumor cells compared to stromal cells across tumor indications tested." (PMID 41415295, 2025). "By using a short Sulfo-SMCC linker, the collagen-binding motif TKKTLRT was integrated with the SIRPαFc fusion protein, allowing the blockade of the immune checkpoint molecule CD47 while boosting phagocytosis-mediated tumor inhibition." (PMID 40721833, 2025). "Our model predicts that disrupting the SIRPα-CD47 checkpoint enhances macrophage-mediated phagocytosis, shifting the tumor microenvironment toward a more immune-active state." (PMID 41296731, 2025). "Despite the CD47-SIRPα axis being widely studied in cancer, its pro-tumor mechanism and blockade therapy are seldomly reported in HCC." (PMID 40523887, 2025). "To study the influence of anti-CD47 treatment on the digital twins of the experimental mice used in this study, we simulated its effect by modifying the tumor killing parameter μ in the ODE model." (PMID 40845580, 2025). "We show tumor-specific binding and CD47 blocking by the SIRPα-αMSLN LicMAb even in the presence of healthy CD47-expressing cells." (PMID 40402266, 2025).
tumor (continued). "BI 765063 prevents ligand binding between SIRPα and CD47 by binding to SIRPα, thereby blocking cellular signaling that would lead to a decrease in anti-tumor substances (e.g., macrophages and DCs) in myeloid cells." (PMID 40356928, 2025). "The CD47-SIRPα axis plays a role in tumor evasion in the process of phagocytosis mediated by macrophages, dendritic cells, and other phagocytic cells." (PMID 40861801, 2025). "Conversely, CD47 blockade has been shown to shift TAMs toward the pro‐inflammatory M1 phenotype, enhancing anti‐tumour immunity and facilitating phagocytic clearance." (PMID 41195773, 2025). "Several preclinical models demonstrate that CD47-overexpressing NK cells show prolonged circulation and improved tumor localization." (PMID 40723807, 2025). "QPCTL is a pyroglutaminase that facilitates CD47-SIRPα interaction, thus inhibiting macrophage-mediated phagocytosis of tumor cells." (PMID 40055311, 2025). "The efficacy of anti-CD47 immunotherapy in SG tumors depends on CD47 expression within the tumor microenvironment, emphasizing the need for histology-driven approaches." (PMID 41164198, 2025). "Altogether, these results characterize the aptamer-siRNA chimera as capable of selectively binding to tumor-infiltrating Treg cells, being efficiently internalized, and inducing effective CD47 knockdown." (PMID 41402667, 2025). "The interaction between the SIRPα ligand on myeloid cells, such as macrophages, and the abundant CD47 on tumor cells results in the phosphorylation of SIRPα’s cytoplasmic tail, initiating an inhibitory signaling cascade known as the “don’t eat me” signal." (PMID 41350707, 2025). "In tumor-bearing mice, HDACi monotherapy only marginally delayed tumor progression, while the concurrent neutralization of CD47 exhibited potent anti-tumor effect through re-educating TAMs towards a tumoricidal phenotype." (PMID 39994810, 2025). "In the GBM TME, the inhibition of CD47 can effectively re-educate GAMs to unlock the therapeutic potential of tumor cell phagocytosis." (PMID 40548122, 2025). "CD47-blocking therapies showed preclinical effectiveness in promoting phagocytosis across various tumor types and produced an antitumor cytotoxic T-cell immune response." (PMID 41562047, 2025). "On the other hand, the CD47–SIRPα binding transmits a “don’t eat me” signal, preventing phagocytosis of tumor cells by neutrophils and macrophages." (PMID 40948940, 2025). "Radiotherapy similarly induces anticancer immunity by promoting ICD, upregulating MHC class I expression, enhancing tumor antigen presentation, downregulating CD47 mediated signals, and producing reactive oxygen species." (PMID 41163421, 2025). "Tumor cells exploit the SIRPα-CD47 immune checkpoint to evade the immune system by inhibiting antigen-presenting cell phagocytosis." (PMID 40959090, 2025). "GW in combination with anti-CD47 therapy effectively blocked primary foci metastasis, eliminated existing liver metastases, and controlled primary tumours." (PMID 39025845, 2024). "In many preclinical studies, blocking the CD47-SIRPα axis has been proven to enhance the macrophage-mediated killing of tumor cells, resulting in tumor growth inhibition." (PMID 39335665, 2024). "Although both CD38high and CD38low tumor cell lines expressed high levels of CD47, ISB 1442 phagocytosis was similar to that of high affinity bivalent hu5F9." (PMID 38448430, 2024). "In cancer, CD47 not only inhibits phagocytosis via SIRPα but also affects tumor growth and metastasis through integrin signaling and modulation of angiogenesis." (PMID 39039207, 2024). "In our present study, we characterized a novel role of NRF-1 in melanomagenesis as a regulator of the major innate immunity checkpoint, CD47, in tumor cells." (PMID 39742254, 2024). "Differentiation cluster 47 (CD47), a glycoprotein widely expressed on the cell surface, regulates tumor invasion and metastasis." (PMID 38404571, 2024).
tumor (continued). "Taken together, TUG1 upregulate PD‐L1 to inhibit the antitumor immune response of CD8+ T cells, and upregulates CD47 to inhibit the phagocytosis of macrophages, ultimately promoting tumor immune escape." (PMID 38981064, 2024). "Here, the authors show that MLKL-driven necroptosis contributes to PDAC early-stage metastasis by inducing tumour CD47 upregulation and macrophage extracellular traps formation." (PMID 39025845, 2024). "Monoclonal antibodies against CD47 inhibit tumor growth and prolong survival in mouse models of GBM44." (PMID 39627379, 2024). "Mechanistically, MLKL-driven necroptosis recruits macrophages, enhances the tumor CD47 ‘don’t eat me’ signal, and induces macrophage extracellular traps (MET) formation for CXCL8 activation." (PMID 39025845, 2024). "It has been well established that although CD47 blockade can lower the phagocytic threshold, prophagocytic (“eat me”) signals, such as via Fc/FcR engagement, are needed to drive tumor cell engulfment by macrophages." (PMID 38828721, 2024). "The intestinal flora alters TME through STING signal transduction at the tumor site, leading to an anti-CD47 immunotherapy effect." (PMID 38835386, 2024). "Taken together, these results demonstrate that CD47 × PD‐L1 BisAb treatment boosts tumor‐resident CD8+ TIL generation and can engender these populations with superior cytokine productivity." (PMID 39584189, 2024). "Immunohistochemistry and confocal microscopy assessed CD47 expression in tumor and adjacent tissues, while immunofluorescence evaluated CD47 on tumor-infiltrating T lymphocytes." (PMID 39652550, 2024). "It should be noted, however, that exosomal surface expression of CD47 decreased after tumor surgery in these patients." (PMID 38743146, 2024). "For instance, the integration of high-affinity CD47nb into the synchronized lysis circuit (eSLC) allows bacteria to colonize at tumor sites and release CD47nb locally, targeting tumor cells expressing CD47." (PMID 39165407, 2024). "Surprisingly, in this study, targeting CD47 was found to promote tumor angiogenesis, indicating a deviation from the expected anti-angiogenic effect." (PMID 38398223, 2024). "For instance, previous studies have shown that combined application of CD47 with PD-1/PD-L1 blockade can result in stronger anti-tumor effects." (PMID 38331898, 2024). "We found that CD47 × PD‐L1 BisAb resulted in robust anti‐tumor immunity by enhancing antigen‐specific tumor‐resident CD8+ TIL with superior cytokine production." (PMID 39584189, 2024). "This paradox arises because necroptosis upregulates the “don’t eat me” signal CD47 on tumor cells, enabling them to evade immune surveillance." (PMID 39575419, 2024). "For example, tumor cells express a ‘don’t eat me signal’ CD47, which interacts with TAM-expressed signal regulatory protein (SIRP)α to stop tumor cells from being phagocytosed." (PMID 39588367, 2024). "The presence of CD47 on tumor cells hinders macrophages in the immune system from undergoing phagocytosis, and noteworthy outcomes have been documented in clinical trials that focus on CD47 in various blood cancers and solid tumors." (PMID 38543240, 2024). "Targeting CD47 with monoclonal antibodies or other inhibitors can enhance macrophage-mediated phagocytosis of cancer cells, promoting tumor clearance." (PMID 39040441, 2024). "Some tumor cells exhibit CD47 and/or SIRPα overexpression, utilizing the “don't eat me” signaling to evade immune response and facilitate tumor invasion." (PMID 39240588, 2024). "Combining radiotherapy with CD47/SIRPα blockade can further enhance the phagocytosis of macrophages, leading to a significant reduction in tumor growth." (PMID 38462636, 2024). "We also developed a scoring system to distinguish different levels of CD36 and CD47 expression in tumor cells, based on the data from the escalation phase." (PMID 39627379, 2024). "CD47 also stimulates tumor-initiating cells, sometimes called cancer stem cells, to differentiate into mature cells." (PMID 38218979, 2024).
tumor (continued). "The expression of specific TAMs, such as CD47, CD68, and CD163, has been studied in NPC and is linked to various aspects of tumor behavior, prognosis, and potential therapeutic strategies." (PMID 39682556, 2024). "NILK-2401 combines promising preclinical activity with limited potential side effects due to the tumor-targeted blockade of CD47 and low immunogenicity and is planned to enter clinical testing." (PMID 38720892, 2024). "Infiltration by CD68-IT cells in the tumor depended on histological type and the expression of CD47." (PMID 39201801, 2024). "The combination of tumor-specific antibodies and decoys of the innate immune checkpoint CD47 secreted by gene-modified T cells potentiate targeted phagocytosis of tumor cells." (PMID 38828721, 2024). "Collectively, these findings highlighted the promising prospects of a dual blockade strategy targeting CD47/SIRPα and PD-1/PD-L1, in combination with radiotherapy, as an effective approach for achieving optimal tumor elimination." (PMID 38462636, 2024). "This approach guides immune cells to tumor sites by targeting CD47 checkpoint receptors expressed on cancer cells." (PMID 38785789, 2024). "In our patient cohort consisting of various STS, half of the samples had more than 2/3 of the total tumor area positive on CD47 staining." (PMID 38493445, 2024). "Targeting CD47 and blocking the CD47–SIRPα interaction can eliminate this inhibitory signal and enhance macrophage phagocytosis, allowing T cells to fulfill their tumor-killing role in the TME." (PMID 39350256, 2024). "In TNBC mouse models, an anti-CD47 antibody conjugated with the cytotoxic drug mertansine demonstrated significant inhibition of tumor growth compared to the administration of the drug alone." (PMID 39409110, 2024). "Using murine models with genetically color-coded macrophages (Ccr2RFP) and microglia (Cx3cr1GFP), both populations were found to participate in anti-CD47 enhanced tumor cell phagocytosis in vivo." (PMID 38786045, 2024). "Many studies discussed before showed that immunohistochemical CD47 expression is increased in relation to pathological tumor stage, tumor grade, recurrence, and presence of distant metastases." (PMID 39795582, 2024). "Myeloid cells, including macrophages, express signal regulatory protein alpha (SIRPα), a receptor that recognizes CD47 and, when binds to it, provides a down-regulatory signal preventing the phagocytosis of tumor cells." (PMID 39003350, 2024). "NCD47‐SLAMF7 consists of a signaling peptide, a nanobody that can block the function of CD47, and the extracellular region of SLAMF7, which can target tumor cells and mask their CD47 molecules." (PMID 39713206, 2024). "When tested in combination with the anti-CD47 monoclonal antibody magrolimab, the combination enhanced anti-tumor effects compared to monotherapy." (PMID 38786045, 2024). "Targeting CD47 increased tumor cell destruction by macrophages and resulted in reduced tumor growth and prolonged survival in mice." (PMID 38164150, 2024). "Nevertheless, CD47 isoform functions and switching during cellular transformation, tumorigenesis and tumor development, and neurotransmission require further investigation." (PMID 38426113, 2024). "When anti-CD47 antibodies were administered, antibody-dependent phagocytosis was activated as well as TAMs being converted into an anti-tumor state which lead to suppression of tumor." (PMID 38892394, 2024). "Inhibition of CD47 emerges as a prospective strategy to enhance the elimination of tumor cells across diverse cancer types." (PMID 38217016, 2024). "Tumor cells express “self” signals (e.g., CD47 molecules) and prevent the phagocytosis of macrophage." (PMID 38383737, 2024). "Despite the demonstrated anti-tumor effects of immune checkpoint inhibitors (ICIs) in various cancer types, eradicating tumor cells remains challenging, including in the case of CD47 blockade therapy." (PMID 38532108, 2024).
tumor (continued). "CD47, when overexpressed in tumor cells, can serve as a potential target for the directed delivery of expression cassettes with genetically encoded therapeutic agents or for the targeting of viral oncolytics." (PMID 38247566, 2024). "The CD47 protein is a 50 kDa type I transmembrane glycoprotein that is ubiquitously expressed in healthy cells but is overexpressed in various tumor cells." (PMID 38983860, 2024). "This highlights the delicate balance between pro-phagocytic signals like CALR and anti-phagocytic signals such as CD47 in the immune system’s ability to recognize and eliminate tumor cells." (PMID 39682299, 2024). "The investigation aimed to elucidate the potential impact of CD47 interaction with TNFRSF9 within the tumor immune microenvironment (TIME) on CD8 + T cell functionality and its consequent effect on the prognosis of patients with malignant tumors." (PMID 38720108, 2024). "Monotherapy with anti-CD47 antibodies leads to inhibition of tumor growth in SK-OV-3 OC cells and inhibition of growth, migration, and invasion of TOV OC." (PMID 38892394, 2024). "Lastly, we performed a third tumor challenge on second challenge survivors with untreated B16F10 CD47 KO cells (chromosomally stable and regular proliferating)." (PMID 37066426, 2024). "Conversely, in CC, inhibition of LSD1 (ORY-1001) directly reduced PD-L1 and CD47 on the surface of tumor cells." (PMID 39629133, 2024). "The concurrent administration of galectin-3 and CD47 extensively promoted the remodeling of TAMs and phagocytosis, resulting in an increased T cell response and suppressed tumor growth in an in vivo experimental peritoneal metastasis model." (PMID 39519285, 2024). "Next, we wondered how the activated IFN-I signaling pathway affects tumor cells in response to CD47-SIRPα blockade." (PMID 38982116, 2024). "CD24 and CD47 are two types of membrane proteins broadly expressed by tumor cells, which can bind to signal proteins on the surface of macrophages, trigger the “don’t eat me” signal, and inhibit macrophage phagocytosis, thus escaping anti-tumor immunity." (PMID 38787372, 2024). "An added benefit of anti-CD47 is that it not only promotes phagocytosis but can promote M1 macrophage polarization which should promote a more immunologically “hot” tumor." (PMID 39194679, 2024). "More specifically, CD47 serves as a DEM on tumor cells by escaping phagocytic elimination mediated by TAMs and other phagocytes through its interaction with signal regulatory protein-α (SIRP-α), which is expressed on macrophages." (PMID 39767726, 2024). "The second day after each irradiation, we measured PpIX levels to assess δ‐ALA release, pH levels within the tumor to assess CaCO3 nanoparticle release, and CD47 expression to assess aCD47 release." (PMID 39467056, 2024). "CD47 is a transmembrane receptor expressed on tumor cells that promotes immune invasion by inhibiting the phagocytosis of tumor cells by macrophages." (PMID 39337385, 2024). "In vivo anti-tumor effects of targeting CD47 and angiogenesis were experimented in the HSPCs-CDX model." (PMID 39335665, 2024). "High expression of molecules associated with the CD47-Sirpα signaling pathway has been observed in ESCC tissues and was significantly correlated with deeper penetration depths into tumor tissue and lower survival." (PMID 39678502, 2024). "CD47–SIRPα myeloid checkpoint inhibition has been shown to be effective in enhancing tumor phagocytosis and reducing tumor size in GBM studies." (PMID 38256021, 2024). "CD47 is usually upregulated on the surface of tumor cells, binding to signal-regulatory protein alpha (SIRPα) on phagocytic cells and inhibiting their phagocytic function, creating a “don’t eat me” signal." (PMID 39148736, 2024). "CD47, which has been recognized as an intrinsic immune checkpoint, exhibits extensive overexpression in diverse types of tumor cells." (PMID 38532108, 2024).